TNNC1 (troponin C1, slow skeletal and cardiac type)
Description:
Troponin is the central regulatory protein of striated muscle contraction. Tn consists of three components: Tn-I which is the inhibitor of actomyosin ATPase, Tn-T which contains the binding site for tropomyosin and Tn-C. The binding of calcium to Tn-C abolishes the inhibitory action of Tn on actin filaments.
Synonyms: TN-C; TNNC; CMD1Z; CMH13; TNC
Tractability: Small molecule: a drug acting on it is in phase 2 or 3 trials; a structure with a bound ligand is known; a high-quality ligand is known; it has a high-quality binding pocket; it belongs to a druggable protein family. PROTAC: ubiquitination databases record sites on it; a small molecule that binds it is known.
Target class: Other cytosolic protein
Gene: Protein-coding gene on chromosome 3 (52,451,100 to 52,454,041, reverse strand). Ensembl gene ENSG00000114854.
Subcellular location (Human Protein Atlas): Actin filaments; Mitochondria; Nucleoplasm
Pathways (Reactome):
Muscle contraction: Striated Muscle Contraction
Gene Ontology:
Molecular function: calcium ion binding; calcium-dependent protein binding; protein binding; protein homodimerization activity; troponin I binding; troponin T binding; actin filament binding; cytoskeletal protein binding
Biological process: cardiac muscle contraction; regulation of muscle contraction; ventricular cardiac muscle tissue morphogenesis; cardiac muscle cell contraction; muscle filament sliding; negative regulation of ATP-dependent activity; regulation of muscle filament sliding speed; skeletal muscle contraction; diaphragm contraction; response to metal ion
Cellular component: cardiac Troponin complex; troponin complex; cytosol; sarcomere; contractile muscle fiber
Genetic constraint (gnomAD): Loss-of-function variants: 10 observed, 20.09 expected, observed/expected ratio (o/e) 0.5, 90% interval 0.31 to 0.84. The upper end of that interval is the gene's LOEUF score, 0.84, which puts it in group 3 of 6, group 1 being the genes least tolerant of losing a copy. Missense variants: 115 observed, 225.73 expected, observed/expected ratio (o/e) 0.51, 90% interval 0.44 to 0.6. Synonymous variants: 85 observed, 82.69 expected, observed/expected ratio (o/e) 1.03, 90% interval 0.86 to 1.23.
Gene-disease validity (ClinGen):
ClinGen rates the evidence that TNNC1 causes each of these diseases.
dilated cardiomyopathy 1Z (autosomal dominant): Definitive.
hypertrophic cardiomyopathy (autosomal dominant): Definitive. A condition in which the myocardium is hypertrophied without an obvious cause.
arrhythmogenic right ventricular cardiomyopathy (autosomal dominant): No Known Disease Relationship.
Homologues: Orthologues: chimpanzee TNNC1 (100% identical), rabbit TNNC1 (100% identical), dog TNNC1 (99% identical), mouse Tnnc1 (99% identical), pig TNNC1 (99% identical), rat Tnnc1 (99% identical), guinea pig TNNC1 (99% identical), tropical clawed frog tnnc1 (96% identical), macaque TNNC1 (91% identical), zebrafish tnnc1b (88% identical). Paralogues in human: TNNC2 (63% identical).
Diseases named in the same sentence as TNNC1 in open-access papers:
TNNC1 is named in the same sentence as 47 diseases in open-access papers, as found by Europe PMC text mining. Sharing a sentence is not in itself a finding about the gene and the disease. The quoted sentences say what the papers report.
hypertrophic cardiomyopathy (18 papers, 2014 to 2025). "Variants in TNNC1 reported thus far predominantly cause hypertrophic cardiomyopathy (HCM) resulting from increased Ca2+ sensitivity of force of the cardiomyocytes." (PMID 34502093, 2021). "We note that mutations in the gene that encodes for cardiac troponin C (TNNC1) have been associated with hypertrophic cardiomyopathy, restrictive cardiomyopathy, and ventricular fibrillation." (PMID 32547426, 2020). "The human TNNC1 (OMIM: 191040) mutations are reported to cause hypertrophic cardiomyopathy 13 and dilated cardiomyopathy DCM." (PMID 26815362, 2016). "In our dataset, MYOZ2 (myoz2a), TPM1 (tpm1) and TNNC1 (tnnc1a) have been identified which are previously reported to be linked with diverse forms of dilated and hypertrophic cardiomyopathy." (PMID 26815362, 2016). "More missense mutations, for example A8V, C84Y, E134D, and D145E, in TNNC1 have been reported in hypertrophic cardiomyopathies." (PMID 24817852, 2014). "Mutation A31S in TNNC1 increases Ca2+ sensitivity, which may contribute to causing hypertrophic cardiomyopathy and arrhythmogenesis." (PMID 24817852, 2014). "TNNC1 serves as a crucial structural element in upholding myofibril integrity, potentially causing disruptions in Ca2+ cycling mechanisms and triggering compensatory cardiomyocyte hypertrophy, ultimately culminating in the progression of hypertrophic cardiomyopathy." (PMID 40161384, 2025). "Mutations in TNNC1—the gene encoding cardiac troponin C (cTnC)—that have been associated with hypertrophic cardiomyopathy (HCM) and cardiac dysfunction may also affect Ca2+-regulation and function of slow skeletal muscle since the same gene is expressed in both cardiac and slow skeletal muscle." (PMID 28473771, 2017). "At day 21 of PEPs inhalation, Tnnc1 was down-regulated (p < 0.05) in rat lung, with involvements in cardiac muscle contraction and tissue morphogenesis, dilated cardiomyopathy, and hypertrophic cardiomyopathy." (PMID 31888290, 2019). "Further analysis, of the genes affected within the hypertrophic cardiomyopathy ontology, identified many structural genes including troponin I (Tnni3), troponin T (Tnnt2), troponin C (Tnnc1), α-actin C1 (Actc1) that are important for proper cardiac function." (PMID 24475304, 2014). "We evaluated the hypothesis that myofilament dysfunction is coupled to morphological and functional alterations of cardiomyocyte nuclei in a Tnnc1-targeted knock-in (Tnnc1-p.A8V) mouse model of hypertrophic cardiomyopathy (HCM)." (PMID 41295374, 2025). "During the rest phase (CT30 and CT34), ECM-receptor interaction (e.g., Tnxb, Col4a1, and Col6a1) was the most enriched pathway among genes downregulated in WT KPC mice, while hypertrophic cardiomyopathy (e.g., Des, Tnnc1, and Myl3) was the most enriched pathway among upregulated genes." (PMID 40349340, 2025). "Tnnc1 also regulates cardiac systolic or diastolic function by troponin–tropomyosin complex formation with Tpml and Actcl, etc., and is an important part of the cardiac muscle contraction pathway and hypertrophic cardiomyopathy pathway." (PMID 29154475, 2018). "Furthermore, some of these genes, including TNNC1, TNNT2 and ACTC1, enriched the Hypertrophic cardiomyopathy (HCM) pathway." (PMID 34069910, 2021).
cardiomyopathy (16 papers, 2011 to 2025). A disease of the heart muscle or myocardium proper. "TNNC1, also known as Troponin C Type 1 (slow), was first identified as a mutant gene associated with cardiomyopathy." (PMID 39494275, 2024). "In a recent meta-analysis, TNNC1 conveyed the poorest prognosis of each of the cardiomyopathy-associated troponin genes, with the youngest age of diagnosis and highest rates of death, transplant and ventricular fibrillation." (PMID 36158814, 2022). "Given the central role of cTnC in cardiomyocyte contraction, it is little surprise that a growing number of variants in the TNNC1 gene have been identified in genetic screens for familial cardiomyopathies, both hypertrophic and dilated." (PMID 32038292, 2019). "Additionally, fewer cardiomyopathy-associated pathogenic mutations have been identified in TNNC1 compared to other thin filament genes, such as TNNT2 and TNNI3." (PMID 36158814, 2022). "If it turns out that TNNC1 is only expressed in immature or fetal cardiomyocyte nuclei and not in the adult heart, pathogenic mutations, including A8V, could still disrupt nuclear structure and function early in development and underlie the pathophysiology of cardiomyopathy." (PMID 41295374, 2025). "Among troponins, TNNC1 is the only gene whose role in cardiomyopathies is controversial, including a suggestion of the recessive model of inheritance, despite functional studies indicating the pathogenicity of monoallelic variants." (PMID 32013205, 2020). "In 8 (66.7%), we found de novo variants in known cardiomyopathy genes (TTN, DSP, SCN5A, TNNC1, TPM1, CRYAB, MYH7)." (PMID 32013205, 2020). "In 8/12 probands (66.7%), we found likely causative variants in known cardiomyopathy genes (TTN, DSP, SCN5A, TNNC1, TPM1, CRYAB, and MYH7), which were confirmed as de novo (six DCM, one HCM, and one RCM case)." (PMID 32013205, 2020). "In 6 of 10 cases of sporadic DCM and in single cases of RCM and HCM, we found de novo mutations in genes previously associated with cardiomyopathy (CRYAB, DSP, MYH7, SCN5A, TNNC1, and TTN)." (PMID 32013205, 2020). "To explore the hypothesis that cardiomyocyte nuclear size is altered in sarcomeric cardiomyopathy, we used our previously established Tnnc1-p.A8V knock-in mouse model." (PMID 41295374, 2025). "At the same time, our study found that DAPs TNNC1 is significantly down-expressed as an 18 kDa member of the EF-hand Ca2+-binding protein family in both slow skeletal and cardiac tissue, and this gene has the regulation function of cardiomyopathies." (PMID 36839409, 2023). "It is therefore no mystery why pathogenic mutations in TNNC1 can cause human cardiomyopathy." (PMID 41295374, 2025). "Cardiomyopathy genes, including nine prespecified DCM genes including BCL2-associated athanogene-3 (BAG3), desmoplakin (DSP), LMNA, MYH7, sodium voltage-gated channel, alpha subunit 5 (SCN5A), telethonin (TCAP), cardiac troponin C (TNNC1), TNNT2, and TTN, were sequenced." (PMID 40004816, 2025).
dilated cardiomyopathy (12 papers, 2013 to 2024). Cardiomyopathy which is characterized by dilation and contractile dysfunction of the left and right ventricles. "Hypertrophic and dilated cardiomyopathy causing mutations have been detected mostly in genes of sarcomere proteins such as Mybpc2, Myh7, Tnnt2, Tnnc1, Tnni3, Tpm1, Ttn, Actc1, Myl2, and Myl3." (PMID 38981849, 2024). "The Ventricles-Enriched MYH7, FHL2, TNNC1 and TNNI3 genes were associated with dilated cardiomyopathy (DCM)." (PMID 34088950, 2021). "The male index with a mild dilated cardiomyopathy (DCM) and a pathogenic truncating TTN variant, also carried a variant of unknown significance (VUS) in TNNC1." (PMID 38516780, 2024). "Interestingly, in both the HIV vs. HIV+PSU and WT+PSU vs. HIV+PSU comparisons, Tnnc1, Tnnt2, and Actc1 were found to be majorly involved in the calcium signaling and dilated cardiomyopathy (DCM) signaling pathways." (PMID 37766354, 2023). "Moreover, in dilated cardiomyopathy pathway core enrichment, integrins (Itga1, Itga10, Itga8 and Itgb6) and cellular components of troponin system (Tnni3, Tnnc1 and Tnnt2) appeared modulated, besides Cox and Myh genes." (PMID 24252798, 2013).
ovarian carcinoma (6 papers, 2016 to 2024). A malignant neoplasm originating from the surface ovarian epithelium. "TNNC1 is a component of the calcium-regulatory complexes and has been implicated in driving the aggressive behaviors of ovarian cancer." (PMID 37511982, 2023). "In conclusion, a Ca2+-dependent signaling complex (FAK/CREB/TNNC1) was implicated in fostering the metastatic potential of ovarian cancer." (PMID 29416706, 2018). "Furthermore, siRNA- knockdown of TNNC1 abrogated the stimulatory effect of microfibrillar-associated protein 5 (MFAP5) on ovarian cancer cell motility, indicating TNNC1 as a downstream effector of MFAP5." (PMID 29416706, 2018). "Building on our previous findings, the present study aimed to further explore the potential of bepridil as a targeted therapeutic agent for the modulation of TNNC1 signaling and the suppression of the metastatic phenotype of ovarian cancer cells." (PMID 37511982, 2023). "Our previous research demonstrated significantly elevated TNNC1 expression in SKOV-3-13 compared to SKOV-3, highlighting the pivotal role of TNNC1 in accelerating the malignant progression of ovarian cancer cells through the activation of EMT." (PMID 37511982, 2023). "Corroborating our previous work, this study demonstrates the effectiveness of bepridil—a pharmacological inhibitor of TNNC1—in both ovarian cancer cell lines." (PMID 37511982, 2023). "Specifically, it was shown that TNNC1 is overexpressed in epithelial ovarian cancer cells, as well as human high-grade serous ovarian cancer tissue." (PMID 29416706, 2018). "TNNC1 was over-expressed in ovarian cancer cells, and elevated TNNC1 expression regulated epithelial cancer cell motility and invasion potential via cytoskeleton reorganization." (PMID 27713166, 2017). "Suppression of TNNC1 expression can control metastasis in gastric and ovarian cancers." (PMID 39494275, 2024). "Other researches also showed that MFAP5 mediates ovarian cancer cell motility and invasion potential through FAK/CREB/TNNC1 signaling pathways, suggesting that it may be a new modality of ovarian cancer treatment." (PMID 30899449, 2019).
cardiac hypertrophy (3 papers, 2015 to 2025). "In addition, we observed that genes associated with cardiac hypertrophy, such as NPPA, NPPB, TNNC1, and DES, were markedly upregulated in the mutant compared with WT iPSC-CMs." (PMID 40779454, 2025).
Desminopathy (2 papers, 2024 to 2025). "Less frequent but notable associations include DES (linked to desminopathy), PLN, SCN5A, and TNNC1, the latter contributing to the DCM phenotype in a smaller subset of patients." (PMID 39857686, 2025).
lung adenocarcinoma (2 papers, 2024 to 2025). A carcinoma that arises from the lung and is characterized by the presence of malignant glandular epithelial cells. "In lung adenocarcinoma, TNNC1 overexpression can attenuate the invasion and metastasis of tumor cells, functioning as a tumor suppressor gene." (PMID 39494275, 2024). "This study analyzed the characteristics of a calcium-related prognostic genes (CRPGs) signature in lung adenocarcinoma (LUAD) for prognostic value and explored TNNC1 as a potential therapeutic target for erlotinib resistance." (PMID 40433361, 2025).
tongue cancer (2 papers, 2017 to 2024). A malignant neoplasm affecting the tongue. "Studies have shown that TNNC1 is a promising biomarker for metastasis of ovarian and tongue cancers." (PMID 38730335, 2024).
Alzheimer disease (1 paper, 2024). A progressive, neurodegenerative disease characterized by loss of function and death of nerve cells in several areas of the brain leading to loss of cognitive function such as memory and language. "The down-regulated DEGs in DM versus NN were primarily focused on ribosome (approximately 80 DEGs, including RPL37 and RPS11), Alzheimer’s disease (about 86 DEGs), and cardiac muscle contraction (about 22 DEGs, such as UQCRQ and TNNC1)." (PMID 38660519, 2024).
colon cancer (1 paper, 2024). "Compared to the normal colon epithelial cell line (CCD841CoN), TNNC1 expression levels were higher in colon cancer cell lines, including HCT116, HT29, and SW620." (PMID 39494275, 2024). "Notably, TNNC1 expression levels were high in all the colon cancer cell lines, particularly in SW480 cells." (PMID 39494275, 2024).
diabetes mellitus (1 paper, 2020). A metabolic disorder characterized by abnormally high blood sugar levels due to diminished production of insulin or insulin resistance/desensitization. "The results of this research may help explain the induction of tacrolimus-induced posttransplantation diabetes mellitus via the low expression of muscle genes including Tpm3, Tnnc1, Tnnt1, Tnni3, Hrh3, Apln, S1pr3, and Cxcl12." (PMID 31998808, 2020).
familial dilated cardiomyopathy (1 paper, 2019). A a genetic form of heart disease that occurs when heart (cardiac) muscle becomes thin and weakened in at least one chamber of the heart, causing the open area of the chamber to become enlarged (dilated). "Familial dilated cardiomyopathy (DCM), clinically characterized by enlargement and dysfunction of one or both ventricles of the heart, can be caused by variants in sarcomeric genes including TNNC1 (encoding cardiac troponin C, cTnC)." (PMID 32038292, 2019).
liver cancer (1 paper, 2024). An epithelial or non-epithelial malignant neoplasm that arises from the liver. "For example, TNNC1 can mediate the migration of liver cancer cells through PI3K/AKT." (PMID 39494275, 2024).
Lymphatic Metastasis (1 paper, 2017). Transfer of a neoplasm from its primary site to lymph nodes or to distant parts of the body by way of the lymphatic system. "In conclusion, MFAP5 and TNNC1 could be potential markers for predicting occult cervical lymphatic metastasis and prognosis of oral tongue carcinoma." (PMID 27713166, 2017).
metastasis (1 paper, 2017). The spread or migration of cancer cells from one part of the body (where they first appeared) to another. "Thus, TNNC1 appeared to be more sensitive than MFAP5 in predicting the prognosis of TSCC and its occult cervical lymphatic metastasis." (PMID 27713166, 2017).
myocardial infarction (1 paper, 2025). Gross necrosis of the myocardium, as a result of interruption of the blood supply to the area, as in coronary thrombosis. "The troponin genes (TNNC1, TNNT2, TNNI3), the creatine kinase gene (CKM), and the brain natriuretic peptide gene (NPPA) are recognized biomarkers of myocardial infarction." (PMID 40433126, 2025). "Notably, JUP and VDAC3 exhibited a high correlation with myocardial infarction biomarkers; however, JUP also demonstrated a significant correlation with TNNC1, TNNT2, TNNI, CKM, and NPPA (P < 0.05)." (PMID 40433126, 2025).
Noonan syndrome with multiple lentigines (1 paper, 2023). A rare multisystem genetic disorder characterized by lentigines, hypertrophic cardiomyopathy, short stature, pectus deformity, and dysmorphic facial features. "This is also the case for 8/14 syndromic HCM (CACNA1C, FLNC, PRKAG2, PTPN11 (Noonan), PTPN11 (Noonan syndrome with multiple lentigines), RAF1, RIT1, TTR), 3/12 DCM (DES, TNNC1 and TNNT2), and 2/6 ARVC (JUP, TMEM43) gene-disease pairs." (PMID 37872640, 2023).
oral cancers (1 paper, 2017). "However, the relationship between MFAP5 and TNNC1 in oral cancers remains unclear." (PMID 27713166, 2017).
sarcopenia (1 paper, 2024). Progressive decline in muscle mass due to aging which results in decreased functional capacity of muscles. "Our results suggested that BDNF, JAK2, RhoC, Myh6, Stat5a, Tnnc1, and other genes may mediate the beneficial effects of exercise on sarcopenia through these pathways." (PMID 39309455, 2024). "Transcriptomic analysis identified BDNF, JAK2, RhoC, Myh6, Stat5a, and Tnnc1 as core target genes that may mediate the effects of different exercise intervention stimuli through the JAK-STAT, cGMP-PKG, and Rap1 pathways to improve the skeletal muscle phenotype of sarcopenia." (PMID 39309455, 2024).
Ventricular arrhythmia (1 paper, 2024). "Also, TNNI3 mutation carriers have lower survival than MYBPC3 and MYH7 mutation carriers, and TNNC1 mutation carriers have a higher risk of developing fatal ventricular arrhythmias." (PMID 38540296, 2024).
viral myocarditis (1 paper, 2021). Myocarditis that is caused by an infection with a viral agent. "Subsequently, we learned intermolecular interactions of herbal components and their targeting heart-tissue-specific CHRM2, FABP3, TNNC1, TNNI3, TNNT2, and SCN5A and cardiac-myocytes-specific IL6, MMP1, and PLAT coupled with viral myocarditis." (PMID 34456633, 2021).